ENSG00000272896 (novel protein)
Gene: Protein-coding gene on chromosome 9 (136,791,379 to 136,800,595, forward strand). Ensembl gene ENSG00000272896.
Genetic constraint (gnomAD): Missense variants: 67 observed, 50.56 expected, observed/expected ratio (o/e) 1.33, 90% interval 1.09 to 1.62. Synonymous variants: 24 observed, 18.54 expected, observed/expected ratio (o/e) 1.29, 90% interval 0.94 to 1.78.